ZNF609 (zinc finger protein 609)
Description:
Transcription factor, which activates RAG1, and possibly RAG2, transcription. Through the regulation of RAG1/2 expression, may regulate thymocyte maturation. Along with NIPBL and the multiprotein complex Integrator, promotes cortical neuron migration during brain development by regulating the transcription of crucial genes in this process. Preferentially binds promoters containing paused RNA polymerase II. Up-regulates the expression of SEMA3A, NRP1, PLXND1 and GABBR2 genes, among others. [Isoform 2]: Involved in the regulation of myoblast proliferation during myogenesis.
Synonyms: KIAA0295
Tractability: PROTAC: UniProt records ubiquitination sites on it; ubiquitination databases record sites on it; its protein half-life has been measured.
Gene: Protein-coding gene on chromosome 15 (64,460,578 to 64,686,068, forward strand). Ensembl gene ENSG00000180357.
Subcellular location: Nucleus; Nucleus (Isoform 2)
Subcellular location (Human Protein Atlas): Nucleoplasm; Cytosol
Gene Ontology:
Molecular function: DNA-binding transcription factor activity, RNA polymerase II-specific; promoter-specific chromatin binding
Biological process: regulation of myoblast proliferation; positive regulation of neuron migration; positive regulation of transcription by RNA polymerase II; regulation of transcription by RNA polymerase II
Cellular component: nucleoplasm; nucleus
Genetic constraint (gnomAD): Loss-of-function variants: 11 observed, 109.91 expected, observed/expected ratio (o/e) 0.1, 90% interval 0.062 to 0.17. The upper end of that interval is the gene's LOEUF score, 0.17, which puts it in group 1 of 6, group 1 being the genes least tolerant of losing a copy. Missense variants: 1,530 observed, 1,825.9 expected, observed/expected ratio (o/e) 0.84, 90% interval 0.8 to 0.87. Synonymous variants: 635 observed, 684.27 expected, observed/expected ratio (o/e) 0.93, 90% interval 0.87 to 0.99.
Homologues: Orthologues: chimpanzee ZNF609 (99% identical), macaque ZNF609 (98% identical), dog ZNF609 (97% identical), pig ZNF609 (97% identical), rabbit ZNF609 (96% identical), mouse Zfp609 (94% identical), rat Zfp609 (94% identical), guinea pig ZNF609 (92% identical), tropical clawed frog znf609 (72% identical), zebrafish znf609a (61% identical), zebrafish znf609b (60% identical), Drosophila melanogaster sbb (28% identical). Paralogues in human: ZNF608 (45% identical).
Diseases named in the same sentence as ZNF609 in open-access papers:
ZNF609 is named in the same sentence as 44 diseases in open-access papers, as found by Europe PMC text mining. Sharing a sentence is not in itself a finding about the gene and the disease. The quoted sentences say what the papers report.
Hirschsprung disease (7 papers, 2017 to 2021). Hirschsprung disease (HSCR) is a congenital intestinal motility disorder that is characterized by signs of intestinal obstruction due to the presence of an aganglionic segment of variable extent in the terminal part of the colon. "In Hirschsprung disease, the level of AKT3 scaled up with that of circ-ZNF609, while miR-150-5p expression was inversely associated with circ-ZNF609 and AKT3." (PMID 31484561, 2019). "For example, in Hirschsprung’s disease, circRNA ZNF609 functions as a competitive endogenous RNA (ceRNA) to regulate AKT3 expression by sponging miR-150-5p." (PMID 29383123, 2017).
glioma (6 papers, 2021 to 2022). A benign or malignant brain and spinal cord tumor that arises from glial cells (astrocytes, oligodendrocytes, ependymal cells). "The expression of miR-378b was negatively correlated with ZNF609 and SLC2A1 and ZNF609 expression was positively associated with SLC2A1 in the clinical glioma samples." (PMID 34520391, 2021). "Furthermore, the association between circ-ZNF609 and clinical features of glioma was analyzed." (PMID 33976745, 2021). "It is of great significance to determine the potential molecular mechanism of circ-ZNF609 in glioma." (PMID 35938040, 2022). "Then, we conducted experiments to explore the effects of circ-ZNF609-wt and circ-ZNF609-mut on glioma cell." (PMID 33976745, 2021). "Then, we detected the biological function of circ-ZNF609 on cell proliferation, migration and invasion in glioma cell lines." (PMID 33976745, 2021). "We measured the expression of circ-ZNF609 in glioma cell lines, and found that circ-ZNF609 expression was markedly increased in glioma cell lines compared to HEB." (PMID 33976745, 2021). "This study aimed at exploring the role and mechanism of circRNA RNA ZNF609 (circ-ZNF609) in the occurrence and development of glioma." (PMID 33976745, 2021). "In this study, we focus on the basic function of ZNF609 in the modulation of glioma, and the clinical value of ZNF609 is needed to explore in future studies." (PMID 34520391, 2021). "In glioma cells, the mRNA and protein expression of E-cadherin was enhanced, while Vimentin was reduced by the inhibition of ZNF609." (PMID 34520391, 2021). "Firstly, we identified that circ-ZNF609 expression was significantly elevated in glioma tissues and cell lines by qRT-PCR assay." (PMID 33976745, 2021). "Firstly, we detected the expression of circ-ZNF609 in glioma tissues and normal control tissues by conducting qRT-PCR assay." (PMID 33976745, 2021). "Elevated circ‐ZNF609 expression led to increased migration and invasion of glioma cells both in vitro and in vivo whereas silencing circ‐ZNF609 decreased migration and invasion of glioma cells." (PMID 34697887, 2021). "To confirm the functional interaction between circ-ZNF609 and miR-1224-3p in glioma cells, we conducted the rescue experiment using qRT-PCR assay, CCK8 assay, EdU assay and transwell assay." (PMID 33976745, 2021). "The glucose uptake, lactate product, and ATP production in glioma cells were suppressed by ZNF609 knockdown." (PMID 34520391, 2021). "In the present investigation, we found that the silencing of ZNF609 repressed cell survival, invasion, and glycolysis and stimulated cell apoptosis in glioma cells." (PMID 34520391, 2021). "In this study, we verified a circRNA deriving from the ZNF609 gene locus, named circ-ZNF609 whose expression was increased in glioma." (PMID 33976745, 2021). "After analyzing, we found that circ-ZNF609 expression was interrelated to the poor prognosis of glioma patients." (PMID 33976745, 2021). "The inhibition of miR-378b or the enhancement of SLC2A1 reversed ZNF609 depletion-regulated glioma cell proliferation in vitro." (PMID 34520391, 2021). "It proposed a novel mechanism of circ-ZNF609 in regulating the progression of glioma." (PMID 35938040, 2022). "It implies that ZNF609 modulates glioma progression by miR-378b/SLC2A1 axis." (PMID 34520391, 2021). "The results indicated that the level of circ-ZNF609 in glioma was markedly increased." (PMID 33976745, 2021). "In our findings, we suggest that circ-ZNF609 might significantly promote the proliferation, migration and invasion of glioma cells through the miR-1224-3p/PLK1 axis, whose function might involve molecular targets beneficial for diagnosing and treating glioma." (PMID 33976745, 2021). "The silencing of ZNF609 stimulated the apoptosis of glioma cells." (PMID 34520391, 2021). "In vivo, xenotransplanted tumor model also showed that overexpression of circ-ZNF609 could promote in vivo glioma growth." (PMID 33976745, 2021).
glioma (continued). "Inhibition of circ-ZNF609 could obviously suppress glioma cell proliferation, migration and invasion, while overexpression of circ-ZNF609 promoted glioma growth and metastasis." (PMID 33976745, 2021). "Meanwhile, the ZNF609 depletion inhibited the invasion and migration of glioma cells." (PMID 34520391, 2021). "In this study, we were interested the function of circular RNA ZNF609 in modulating glioma." (PMID 34520391, 2021). "Overall, we concluded that circ-ZNF609 might participate in the progression of glioma through sponging miR-1224-3p to increase the expression level of PLK1." (PMID 33976745, 2021). "Besides, the expression level of circ-ZNF609 in high grade glioma was higher than that in low grade glioma." (PMID 33976745, 2021). "MiR-378b and SLC2A1 may just one of the mechanisms of ZNF609-meidated glioma progression and other potential mechanisms are needed to investigate to comprehensively understand the function of ZNF609 in glioma." (PMID 34520391, 2021). "In conclusion, our study suggests that circ-ZNF609 might act as an oncogene to promote glioma progression via regulating miR-1224-3p/PLK1 axis." (PMID 33976745, 2021). "Remarkably, knockdown of ZNF609 by siRNA in glioma cells reduced cell viabilities and Edu-positive." (PMID 34520391, 2021). "The depletion of ZNF609 suppressed glioma cell growth in the nude mice." (PMID 34520391, 2021). "Overall, elevated expression of circ-ZNF609 markedly promoted glioma growth in vivo." (PMID 33976745, 2021). "All above results proved that circ-ZNF609 could promote cell proliferation, migration and invasion in glioma." (PMID 33976745, 2021). "Besides, in vitro and in vivo assays demonstrated that circ-ZNF609 was positively interrelated to the growth and metastasis of glioma." (PMID 33976745, 2021). "Besides, correlation analysis verified that circ-ZNF609 expression was negatively interrelated to miR-1224-3p expression in low grade glioma tissues (R2=0.36, p<0.001) and high grade glioma tissues (R2=0.32, p<0.001)." (PMID 33976745, 2021). "Therefore, we concluded that ZNF609 contributed to cell survival and glycolysis of glioma by targeting miR-378b/SLC2A1 axis." (PMID 34520391, 2021). "Silencing circ-ZNF609 could inhibit the proliferation and migration of glioma cells." (PMID 35938040, 2022). "Moreover, transwell assay verified that knockdown of circ-ZNF609 could remarkedly suppress migration and invasion of glioma cell lines." (PMID 33976745, 2021). "ZNF609 and miR-378b may function as potential treatment targets in glioma." (PMID 34520391, 2021). "Therefore, circ-ZNF609 might potentially be applied in the future diagnosis and treatment in glioma." (PMID 33976745, 2021). "Besides, functional assays demonstrated that overexpression of circ-ZNF609 could markedly promote the proliferation, migration and invasion of glioma cells." (PMID 33976745, 2021). "Circ-ZNF609 positively regulated the expression of BTG-2 through competitively binding to miR-134-5p, leading to the proliferation and migration of glioma." (PMID 35938040, 2022). "CCK8 assay, EdU assay and Transwell assay were conducted to detect the effect of circ-ZNF609, miR-1224-3p and PLK1 on proliferation, migration and invasion in glioma cells." (PMID 33976745, 2021). "Hence, circ-ZNF609 might be a potential clinical biomarker and therapeutic target in glioma." (PMID 33976745, 2021). "Materials and methods: Real-time quantitative PCR (qRT-PCR) was applied to measure the expression of circ-ZNF609, miRNA-1224-3p (miR-1224-3p) and Polo-like kinase 1 (PLK1) in glioma tissues and cell lines." (PMID 33976745, 2021). "Mechanically, miR-378b was sponged by ZNF609 and targeted SLC2A1 in glioma cells." (PMID 34520391, 2021). "Moreover, the ZNF609 and SLC2A1 expression were enhanced and miR-378b expression was reduced in the clinical glioma samples." (PMID 34520391, 2021).
glioma (continued). "Mechanistically, circ-ZNF609 could promote PLK1 expression via binding to miR-1224-3p, circ-ZNF609/miR-1224-3p/PLK1 was shown responsible for circ-ZNF609 promoting glioma growth and metastasis." (PMID 33976745, 2021). "Our data showed that miR-378b was sponged by ZNF609 and targeted SLC2A1 in glioma cells." (PMID 34520391, 2021). "Recently, emerging evidence has demonstrated that circ‐ZNF609 is differentially expressed in distinct cancers, such as RCC, CRC, NPC, GC, LC, HCC, prostate cancer, CC, glioma and other diseases such as RMS, HSCR, vascular dysfunction, glaucoma, CNV, neuropathic pain, DM1, DR and LN." (PMID 34697887, 2021). "Mechanistically, circ-ZNF609 might promote PLK1 expression by binding to miR-1224-3p, so as to promote glioma growth and metastasis." (PMID 33976745, 2021). "We found that transfection of circ-ZNF609-wt in glioma cells obviously promoted cell proliferation, migration, and invasion, while transfection of circ-ZNF609-mut could not affect the cell function of glioma cells." (PMID 33976745, 2021). "Furthermore, the results of GEPIA database indicated that linear ZNF609 was much higher in low grade glioma tissues than that in normal tissues." (PMID 33976745, 2021).
nasopharyngeal carcinoma (6 papers, 2020 to 2022). A carcinoma arising from the nasopharyngeal epithelium. "As regards to the oncogenic role of sp1, highly expressed circ-ZNF609 sponged miR-150-5p to promote Sp1 expression, hence supporting the proliferation and metastatic abilities of nasopharyngeal carcinoma cells." (PMID 34499009, 2021). "Circ-ZNF609 regulates nasopharyngeal carcinoma cell growth via modulating miR-188 expression." (PMID 35163336, 2022). "The circRNA originated from ZNF609 has been shown to adsorb miR-150-5p and to upregulate SP1 transcription factor, promoting the proliferation of nasopharyngeal carcinoma cells." (PMID 33432020, 2021).
renal carcinoma (6 papers, 2019 to 2022). A carcinoma arising from the epithelium of the renal parenchyma or the renal pelvis. "Circ-ZNF609 was found to be exceptionally up-regulated and carried out diagnostic biomarker roles in breast cancer, renal cancer, colorectal carcinoma, rhabdomyosarcoma, nasopharyngeal carcinoma, gastric cancer and lung adenocarcinoma." (PMID 34898474, 2021). "For instance, circ-ZNF609 works as a ceRNA to control FOXP4 expression by means of binding to miR-138-5p in renal carcinoma." (PMID 33256799, 2020). "Circ-ZNF609 promoted the development of renal carcinoma by the miR-138-5p/FoxP4 axis." (PMID 34898474, 2021). "For example, circRNA ZNF609 functions as a competitive endogenous RNA to regulate FOXP4 expression by sponging miR-138-5p in renal carcinoma.CircRNA MYLK binds to miR-29a and promotes epithelial-mesenchymal transition and xenograft growth, angiogenesis, and metastasis of bladder cancer." (PMID 30736838, 2019). "By targeted binding to miR-138-5p, circ-ZNF609 upregulated the expression of the transcription factor forkhead box P4 (FOXP4) and promoted the proliferation, migration, and invasion of renal cancer cells." (PMID 35938040, 2022).
breast carcinoma (5 papers, 2020 to 2023). "Circ-ZNF609 was up-regulated in breast cancer and promoted cell proliferation, migration and invasion through sponging miR-145-5p." (PMID 34898474, 2021). "They demonstrated that circ-ZNF609 regulated the miR-145-5p/p70S6K1 axis and could become a potential posttreatment prognostic biomarker in breast cancer." (PMID 35938040, 2022). "Despite the p-values for AUCs of some genes such as AP3B2, BLOC1S1, NUDT13, PTCH1, and ZNF609 being statistically significant in all three breast cancer subtypes, their significance in HER2+ cancers and TNBC were much lower compared to that in ER+/HER2- breast cancer patients." (PMID 37700842, 2023).
cervical cancer (5 papers, 2021 to 2022). A primary or metastatic malignant neoplasm involving the cervix. "A recent study showed that circ-ZNF609 promoted cervical cancer progression as an oncogene via the regulating E2F transcription factor 6 through competitively binding to microRNA-197-3p." (PMID 35135416, 2022). "Their research suggested that the circ-ZNF609/miR-197-3p/E2F6 regulatory axis proposed a new insight into the progression of cervical cancer." (PMID 35938040, 2022). "For example, circ-LRP6 functioned as an oncogenic regulator in esophageal squamous cell carcinoma by targeting the miR-182/Myc signaling and circ-ZNF609 facilitated the development of cervical cancer through the miR-197-3p-mediated E2F6 upregulation." (PMID 34057019, 2021). "Furthermore, circular RNA ZNF609 functions as a ceRNA in regulating E2F transcription factor 6 by targeting microRNA-197-3p to promote cervical cancer progression." (PMID 34288804, 2021).
myocardial infarction (5 papers, 2020 to 2025). Gross necrosis of the myocardium, as a result of interruption of the blood supply to the area, as in coronary thrombosis. "circ-ZNF609, also known as myocardial infarction-associated circular RNA (MICRA), was identified with RNA m6A modification and found to have functions in myoblast, rhabdomyosarcoma, and vascular endothelium." (PMID 35474903, 2022). "The ZNF609 locus is found to generate two different circRNAs that have distinct roles in cardiovascular diseases, the myocardial infarction-associated circular RNA (MICRA) and circZNF609." (PMID 31936839, 2020). "MICRA is an 874 nt long circRNA originated from exon 1 of the ZNF609 gene and proposed as a myocardial infarction biomarker." (PMID 31936839, 2020). "Furthermore, studies have indicated that the circRNA-MICRA, derived from zinc finger protein 609, exhibits lower levels in acute myocardial infarction patients, potentially serving as a biomarker for predicting left ventricular dysfunction." (PMID 39944642, 2025). "Regarding myocardial infarction, a study of high-throughput RNA sequencing found that 3,862 circRNAs are dysregulated in peripheral blood, and the differentially expressed circ-TMEM165, circ-UBAC2, circ-ZNF609, circ-ANKRD12, and circ-SLC8A1 are confirmed in the AC16 cell model." (PMID 37840751, 2023).
prostate carcinoma (5 papers, 2021 to 2022). A carcinoma that arises from epithelial cells of the prostate gland. "Up-regulation of circ-ZNF609 is found to increase the radioresistance of prostate cancer cells by sponging miR-501-3p leading to HK2 up-regulation and enhancing glycolysis." (PMID 36142355, 2022). "Study of circ‐ZNF609 in prostate cancer will provide a novel potential target for the treatment of prostate cancer, although further exploration is needed." (PMID 34697887, 2021). "HK2 was regulated by the circ‐ZNF609/miR‐501‐3p axis in prostate cancer cells, which affected the survival, metastasis, radiation resistance and apoptosis of prostate cancer cells." (PMID 34697887, 2021). "ZNF609 promotes radioresistance by enhancing the glycolysis through miR-501-3p/HK2 signaling in prostate cancer." (PMID 34520391, 2021). "An important finding in prostate cancer is that silencing circ‐ZNF609 increases the radiosensitivity of prostate cancer cells in vivo." (PMID 34697887, 2021). "In addition to this, circ-ZNF609 also enhances the viability, migration, and invasion of prostate cancer cells through the miR-501-3p/HK2 axis, while hindering the apoptosis of prostate cancer cells." (PMID 36142355, 2022). "Circ-ZNF609 was highly expressed in prostate cancer tissues and cells, and silencing it could repress cell viability, inhibit cell migration and invasion, and induce cell apoptosis." (PMID 35938040, 2022). "In conclusion, circ-ZNF609 could promote prostate cancer progression through multiple mechanisms, including regulated glycolysis and metabolism, promoting radioresistance and activating signaling pathways." (PMID 35938040, 2022).